EGFR (epidermal growth factor receptor)
Diseases named in the same sentence as EGFR in open-access papers (continued):
Sharing a sentence is not in itself a finding about the gene and the disease.
ovarian carcinoma (continued). "Previous report has indicated that CXCL1 induces the proliferation of ovarian carcinoma cell through transactivation of epidermal growth factor receptor (EGFR)." (PMID 32782028, 2020). "PAF also transactivates EGFR and downstream pathways in ovarian cancer cells, diversifying the GPCR-mediated signal." (PMID 33392068, 2020). "In ovarian cancer, the overexpression of miR-133b targeted EGFR and inhibited proliferation and invasion abilities by decreasing the phosphorylation of ERK1/2 and AKT pathways." (PMID 31771219, 2019). "In contrast to cytolytic capacity, the production and release of IFNγ out of NK cells were suppressed in the presence of anti-EGFR TKI-sensitized ovarian cancer cells." (PMID 31546690, 2019). "We showed that the expression of MHC I molecules on the surface of the ovarian cancer cells was downregulated due to anti-EGFR sensitization." (PMID 31546690, 2019). "By using a 3D novel engineered ExoProfile chip, diagnostic power of seven markers (EGFR, HER2, CA125, FRα, CD24, EpCAM, and CD9 plus CD63) were evaluated with AUC = 1 in ovarian cancer derived exosomes." (PMID 31718609, 2019). "In summary, our in vitro data show that EGFR-related TKIs and cetuximab are able to enhance antitumoral activity of NK cells in ovarian cancer cells, even if the tumor cells themselves are functionally resistant to the anti-EGFR agents." (PMID 31546690, 2019). "In this preclinical study, we treated different ovarian cancer cell lines with anti-epidermal growth factor receptor (EGFR) TKIs and co-incubated them with natural killer (NK) cells." (PMID 31546690, 2019). "IGF-1R can interact with multiple RTKs that are overexpressed in ovarian cancer, such as EGFR, HER2, ErbB3 and c-Met3." (PMID 31728045, 2019). "In HT1080 fibrosarcoma, A172 gliobastoma, and A2780 ovarian cancer cells, EGFR was also downregulated by Nutlin-3a." (PMID 30910997, 2019). "Alterations of epidermal growth factor receptor (EGFR) have been identified in a variety of human tumors, including lung, breast, head and neck, and ovarian cancers." (PMID 31073278, 2019). "Because we showed that anti-EGFR sensitized ovarian cancer cells enhanced NK cell degranulation, we further evaluated the effect of sensitized target cells on NK cytokine secretion activity." (PMID 31546690, 2019). "We also found that ANGII treatment increased the phosphorylation of EGFR with activation of downstream Gab1 and Shc proteins in ovarian cancer cells." (PMID 30845964, 2019). "In an in vivo mouse model, the EGFR inhibitor erlotinib was found to interfere with spheroid formation, proliferation, and metastatic progression of ovarian cancer cells." (PMID 30568223, 2019). "In human ovarian carcinoma cells, α5β1 coordinates EGFR recycling to the plasma membrane in a way that enhances EGFR-Tyr845 phosphorylation and the serine kinase Akt downstream pathway, thus promoting cell invasion." (PMID 31109009, 2019). "(c) MMP2, EGFR, p-EGFR protein level in ovarian cancer cell under ANGII treatment were measured by Western blot and normalized using GAPDH as a loading control." (PMID 30845964, 2019). "It was also found that a reduced expression of CD44, Nanog, Oct4, CXCL16 and EGFR after ST6GALNAC1 silencing in OCSCs indicated that CD90+ stem cells infected with miRNA against ST6GALNAC1 had weaker self-renewal capacity in ovarian cancer." (PMID 30996686, 2019). "In summary, this study reports, for the first time, an association between EGFR and UGT2A1/2 variants with ovarian cancer risk in AA women." (PMID 31001917, 2019). "In the present study, we showed that anti-EGFR sensitization of ovarian cancer cells enhanced antibody-dependent cellular cytotoxicity (ADCC) of co-incubated NK cells in the presence of cetuximab, which was correlated with increased tumor cell lysis." (PMID 31546690, 2019).
ovarian carcinoma (continued). "As specific TKIs are usually applied over the long term for oncological therapy, the present study aimed to examine the consequences of long-term treatment of anti-EGFR TKIs on ovarian cancer cells displaying intrinsic resistance to anti-EGFR antibodies." (PMID 31546690, 2019). "Therefore, in the present study we analyzed whether a long-term pretreatment of ovarian cancer cells with anti-EGFR TKIs for several days and weeks (“sensitization”) could enable or enhance susceptibility to the EGFR antibody cetuximab in terms of cell viability." (PMID 31546690, 2019). "In summary, our data indicate that EGFR-positive ovarian cancer cells show intrinsic or acquired resistance to anti-EGFR TKIs which cannot be abrogated by the anti-EGFR antibody cetuximab sufficiently." (PMID 31546690, 2019). "The EGFR pathway is activated in more than 70% of ovarian cancer patients and its activation is correlated with platinum resistance and poor prognosis." (PMID 31213009, 2019). "In conclusion, further mechanisms of anti-EGFR resistance as well as the relevance of dual anti-EGFR treatment in ovarian cancer remain to be elucidated." (PMID 31546690, 2019). "The cross-talk between CXCL12-activated CXCR4 and EGFR was suggested to play an important role in cell proliferation signaling in ovarian carcinoma cell lines." (PMID 31703453, 2019). "In ovarian cancer cells, E-cad upregulates ligand-independent EGFR trans-phosphorylation, leading to AKT activation." (PMID 30770786, 2019). "Platinum resistance is a common form of drug resistance in ovarian cancer with several suspected underlying causes including CDK expression, Akt signaling, and EGFR expression." (PMID 30576957, 2019). "IHC studies reported highly variable levels of EGFR expression among malignant ovarian tumors with results ranging from 4 to 100% of ovarian carcinomas expressing EGFR, and an average frequency of 48% across all studies." (PMID 32039018, 2019). "Recent findings confirm that EGFR signaling enhances the migration of human ovarian cancer cells, while VEGF can also play a role in tumor progression via stimulation of proliferation and migration rate of cancer cells." (PMID 31540126, 2019). "Nevertheless, as an oncogene, SPRY4 promotes ovarian cancer invasion through involvement in EGFR-mediated human ovarian cancer progression." (PMID 30390072, 2019). "Overexpression of EGFR is observed in the majority of ovarian cancers; its signaling increases cellular motility, invasiveness, and proliferation of ovarian cancer cells." (PMID 31540126, 2019). "The founding member of the family, the EGFR, is widely overexpressed in ovarian cancer; while HER2 is overexpressed in a subset of ovarian mucinous tumors." (PMID 31426393, 2019). "Previous study also reported that tumor suppressor OPCML inactivates AXL-dependent oncogenic signaling in ovarian cancer and also prevent transactivation of other RTKs such as EGFR and cMET44." (PMID 31043587, 2019). "For example, in non-small-cell lung cancer (NSCLC) and ovarian cancer, the E-to-M transition switches the dependence of carcinoma cells from the EGFR to the AXL receptor tyrosine kinase, thereby yielding resistance to EGFR-targeted therapy." (PMID 30043221, 2018). "OV4 ovarian cancer cells with enforced ST6Gal-I expression were subjected to an unbiased kinomics assay, which revealed that EGFR was one of the most differentially activated kinases in cells with upregulated ST6Gal-I." (PMID 29402301, 2018). "Recently, a report indicated that the level of LSD1 increases in parallel with increased the level of EGFR in ovarian cancer." (PMID 30064416, 2018). "In ovarian cancer, high EGFR expression was shown to be related with shorter disease-free survival (DFS) and OS." (PMID 29249039, 2018). "At a cut-off value of above 5% of tumour cells with positive immunostaining, the expression of EGFR was seen in 37/60 (61.7%) ovarian cancer cases." (PMID 29731973, 2018).
ovarian carcinoma (continued). "Autocrine loop with ERBB2 (EGFR family of tyrosine kinase receptors) induced by YAP to bypass EGFR (epidermal growth factor receptor) inactivation regulates ovarian cancer initiation and progression through Hippo kinases inhibition." (PMID 30223434, 2018). "Down-regulation of EGFR protein either by siRNA or by a synthetic EGFR-down regulating peptide (Herdegradin) can kill prostate and ovarian cancer cells via selective mitophagy by activating the mTORC2/Akt axis." (PMID 30619741, 2018). "Epidermal growth factor receptor (EGFR)-dependent modulation of MT1-MMP surface dynamics was also found to contribute to transition to a more invasive phenotype of ovarian cancer cells." (PMID 30445726, 2018). "In conclusion, hub genes (such as TGFA, EGFR, ErbB2, and MYC) and key pathways (such as the ErbB signaling pathway) closely related to the proliferation of ovarian cancer cells in hypoxia were identified by bioinformatics analysis." (PMID 29482638, 2018). "High expression of CXCR2 or its ligand CXCL1 leads to increased ovarian cancer proliferation, which is believed to be partly mediated by transactivation of EGFR signaling, and the suppression of CXCR2 leads to apoptosis." (PMID 29515768, 2018). "Our previous study confirmed the role of NF-κB signaling through EGFR-transactivated Akt on the CXCR2-driven ovarian cancer progression." (PMID 29515768, 2018). "Many researchers have confirmed that overexpression of epidermal growth factor receptor (EGFR) signaling is closely correlated with poor outcome of ovarian cancer." (PMID 30064416, 2018). "In order to assess the effect of ADAM17 activation on downstream survival signaling in ovarian cancer cells, we investigated activation of the EGFR pathway." (PMID 29662625, 2018). "It was further reported that pertuzumab disrupts EGF-induced heterodimerization of HER2 and EGFR in ovarian cancer cells, expressing both EGFR and HER2." (PMID 30241301, 2018). "A disintegrin and metalloprotease 17 (ADAM17) is highly expressed in ovarian cancer and required for releasing epidermal growth factor receptor (EGFR) ligands like amphiregulin (AREG)." (PMID 29662625, 2018). "More recently, Mehner and colleagues reported the result of immunohistochemical staining of EGFR in tissue microarrays from 488 ovarian cancer patients." (PMID 29731973, 2018). "Decreased HCRP-1 expression is associated with activation of EGFR, and its expression has a significant impact on the prognostic value of EGFR expression in ovarian cancer." (PMID 30518879, 2018). "Some reports showed that high EGFR expression found in ovarian tumors and EGFR signaling was involved in promoting ovarian cancer cell proliferation." (PMID 29510732, 2018). "Upregulation of fibulins (EFEMP1 and HMCN1), which bind EGFR and regulate cell adhesion and migration, correlates with tumour progression and poor prognosis in ovarian cancer." (PMID 28341962, 2017). "Here we have assessed EGFR expression levels in patient-derived tissue microarrays using one of the largest, single institution ovarian cancer patient cohorts to date." (PMID 28740577, 2017). "To examine if SsaI inhibited the EGFR signaling pathway through ST3GalI, we treated the ovarian cancer cell lines with SsaI and found that EGFR expression was down-regulated." (PMID 28423672, 2017). "Mechanistic investigation suggests that GALNT6 modifies EGFR O-glycosylation, thereby, regulating EGFR phosphorylation, which in turn modulates ovarian cancer cell malignant behaviors." (PMID 28388560, 2017). "Here, we investigated the use of EGFR staining as a single prognostic marker in the same ovarian cancer patient cohort." (PMID 28740577, 2017). "To place these null results in the context of prior studies examining EGFR protein expression as a prognostic biomarker in ovarian cancer we have reviewed the current literature." (PMID 28740577, 2017).
ovarian carcinoma (continued). "We also used erlotinib, an EGFR inhibitor, to confirm the significance of EGFR activity in regulating the malignant phenotype of ovarian cancer cells." (PMID 28388560, 2017). "In this study, p-RTK array results showed that GALNT6 regulates the phosphorylation of multiple RTKs in ovarian cancer cells, especially EGFR." (PMID 28388560, 2017). "Efforts using EGFR inhibitors in ovarian cancer patient clinical trials within the general patient population have had only very limited success." (PMID 28740577, 2017). "We demonstrated crosstalk between ST3GalI and EGFR that regulated the migration and invasiveness of ovarian cancer cells." (PMID 28423672, 2017). "We further analyzed three ovarian cancer genomic datasets (TCGA, Bittner, and Lu) and found a linear relationship between ST3GalI and EGFR." (PMID 28423672, 2017). "As a master player, E2F3a was found to be essential in boosting the proliferation of ovarian cancer cells in response to the EGFR-driven mitogenic cell signal." (PMID 28903320, 2017). "Cell surface CDCP1 contributes to EGF/EGFR signaling-mediated migration in ovarian cancer with up-regulation of CDCP1 RNA and protein expression." (PMID 28537886, 2017). "PAFR can also induce chemotherapy resistance in ovarian cancer through transactivating of epidermal growth factor receptor (EGFR)." (PMID 28099922, 2017). "Our study demonstrates that ST3GalI regulates ovarian cancer cell migration and peritoneal dissemination via EGFR signaling." (PMID 28423672, 2017). "Recent studies have shown that the use of GE11 as an EGFR targeting biomolecule enhances the delivery of chemotherapeutic agents to ovarian cancer cells." (PMID 28464952, 2017). "Treatment of OvCAR3 ovarian cancer cells pretargeted with anti-EGFR-FITC with scFvFITC:sFasL resulted in dose-dependent induction of apoptosis with a corresponding loss in cancer cell viability." (PMID 29038485, 2017). "Our study represents one of the largest ovarian cancer patient cohorts assessed by immunohistochemistry for EGFR protein expression and localization." (PMID 28740577, 2017). "To understand the relationship between ST3GalI and EGFR, we investigated the EGFR expression in the ovarian cancer cells with ST3GalI either knocked down or overexpressed." (PMID 28423672, 2017). "Overall, our results and the review of the literature suggest that the prognostic value of EGFR in ovarian cancer cannot be determined by immunohistochemistry alone." (PMID 28740577, 2017). "Although EGFR is an attractive therapeutic target, clinical trials with several EGFR inhibitors have demonstrated modest anti-tumor effects on ovarian cancer." (PMID 28423672, 2017). "We present our results in the context of the current literature focusing on EGFR as a biomarker in ovarian cancer." (PMID 28740577, 2017). "Altered gene expression signature also indicated the reduced c-MET/EGFR signaling in NRF2-silenced ovarian cancer cells." (PMID 29291022, 2017). "We observed that ovarian cancer patients with a high ST3GalI expression demonstrated increased EGFR levels simultaneously." (PMID 28423672, 2017). "A series of studies that have evaluated immunohistochemical (IHC) staining of EGFR in ovarian cancer biopsies has produced unclear results as to the utility of this measure as a prognostic biomarker." (PMID 28740577, 2017). "In some cases, the protein levels decreased in late stage ovarian cancer relative to the healthy controls (e.g. NT-3 growth factor receptor, integrin alpha-1, stem cell factor, epidermal growth factor receptor (EGFR), and interleukin-8)." (PMID 29051715, 2017). "In our studies, the selected receptor was HER2 (human epidermal growth factor receptor 2), a member of the EGFR (epidermal growth factor receptor) family, overexpressed in about 25–30% of breast and ovary cancers, as well as in stomach, lung and other cancers." (PMID 28423057, 2017).
ovarian carcinoma (continued). "Our previous study demonstrated that proinflammatory chemokines such as CCL20, CXCL1-3 and CXCL8 are elicited in ovarian cancer cells via NF-κB- and EGFR-activated signaling pathways." (PMID 27723802, 2016). "Our results show that BTC down-regulates E-cadherin expression and increases cell migration in an EGFR-dependent manner in two human ovarian cancer cell lines (SKOV3 and OVCAR5)." (PMID 27129169, 2016). "Previous studies have demonstrated that epidermal growth factor receptor (EGFR) ligands can induce ovarian cancer cell invasion by down-regulating E-cadherin." (PMID 27129169, 2016). "Overexpression of CXCR2 increased EGFR-transactivated Akt and Erk in ovarian cancer cells such as SKOV-3 and OVCAR-3." (PMID 27723802, 2016). "In the present study, we show that treatment with AREG up-regulated SPRY2 expression by activating the EGFR-mediated ERK1/2 signaling pathway in two human ovarian cancer cell lines, SKOV3 and OVCAR5." (PMID 27835572, 2016). "Our results suggest that betacellulin induces ovarian cancer migration and Slug-dependent E-cadherin down-regulation via EGFR-mediated MEK-ERK and PI3K-Akt signaling." (PMID 27129169, 2016). "A study by Wilken and colleagues showed that trastuzumab sensitized ovarian cancer cells to EGFR-targeted agents." (PMID 26751490, 2016). "Our previous studies have demonstrated that activation of EGFR by different ligands contributes to the down-regulation of E-cadherin and increases the migration and invasion of human ovarian cancer cells." (PMID 27835572, 2016). "As described in detail previously, CXCR2 positive ovarian cancer cells exert highly activated EGFR-downstream signaling such as Akt and Erk and NF-κB, compared to CXCR2 negative cells." (PMID 27723802, 2016). "Using this approach it has been possible to improve tumor-selectivity in i.p. ovarian cancer models via subsequent attachment of epidermal growth factor receptor (EGFR)." (PMID 27056886, 2016). "We previously demonstrated that CXCR2-driven ovarian cancer progression potentiated NF-κB activation through EGFR-transactivated Akt." (PMID 27723802, 2016). "While the targeted EGFR antibody cetuximab has been tested as a single agent in phase II clinical trials with ovarian cancer patients, its effectiveness was limited." (PMID 27888810, 2016). "Future studies will be needed to investigate the molecular mechanisms underlying the different roles of SPRY2 and SPRY4 in the regulation of EGFR-mediated cellular function in human ovarian cancer." (PMID 27835572, 2016). "This is in agreement with the recently reported finding that miR-34a is also a crucial suppressor of the cell cycle promoting factor E2F3a, which was revealed to be a very important regulator in EGFR-driven growth signaling in ovarian cancer." (PMID 26879132, 2016). "For instance, YAP1 was shown to affect activities of cisplatin and EGFR inhibitors in ovarian cancer cells." (PMID 26716514, 2016). "The expression of GPER-1 was significantly increased in ovarian carcinomas compared to pericarcinomatous tissues impendent with the expression of EGFR, ERα, and ERβ." (PMID 27314054, 2016). "Ovarian cancer is characterised by dysregulation of multiple cellular signaling pathways involved in cancer initiation and progression, such as EGFR/ERBB, MAPK, PI3K/AKT/mTOR, WNT, JAK/STAT, NFκB, ERα." (PMID 26964739, 2016). "Although this miRNA has not been described in the context of ovarian cancer, its direct targeting of EGFR is an interesting feature, as EGFR downregulation in ovarian cancer cells is known to lead to BIM upregulation and therefore increased apoptosis." (PMID 26992233, 2016). "An early phase I study assessed the effect of the EGFR-inhibitor gefitinib (Iressa) in various progressed solid tumors including lung, breast, colon, cervix and ovary cancers as well as one case of lymph node positive UrC." (PMID 27283768, 2016).